RAB14 (RAB14, member RAS oncogene family)
Diseases named in the same sentence as RAB14 in open-access papers (continued):
Sharing a sentence is not in itself a finding about the gene and the disease.
asthma (2 papers, 2011 to 2022). "Here we further supported the association on C5 with allergic asthma and furthermore suggested that the entire 9q33.2 region harbouring also Gelsolin and Rab14 is associated with asthma, thus identifying new candidate risk alleles in genes regulating inflammation and immunomodulation." (PMID 21359210, 2011).
lung adenocarcinoma (2 papers, 2020 to 2022). A carcinoma that arises from the lung and is characterized by the presence of malignant glandular epithelial cells. "Further study showed that hsa_circ_0000326 acted as a miR-338-3p sponge to inhibit its activity and thus upregulate its target RAB14, which in turn affected proliferation, migration and apoptosis in lung adenocarcinoma cells." (PMID 32248836, 2020). "We have constructed a model of the mechanism of hsa_circ_0000326 showing that the covalent binding of hsa_circ_0000326 to miR-338-3p increases RAB14 expression and participates in the progression of lung adenocarcinoma." (PMID 32248836, 2020). "As shown in the western blots, RAB14 was a target of miR-338-3p in lung adenocarcinoma cells, and hsa_circ_0000326 overexpression contributed to elevated levels of RAB14." (PMID 32248836, 2020). "Mechanistic studies showed that hsa_circ_0000326 acted as a miR-338-3p sponge and altered the function of miR-338-3p, which in turn upregulated the expression of the downstream target RAB14 and affected the proliferation, migration and apoptosis of lung adenocarcinoma cells." (PMID 32248836, 2020).
lymph node metastasis (2 papers, 2020 to 2023). "RAB14 levels correlated with lymph node metastasis, poor differentiation, a high-grade tumor stage, as well as unfavorable prognostic outcomes for BLCA patients in our previous study." (PMID 37558664, 2023). "In our study, we showed that RAB14 was substantially upregulated and correlated with lymph node metastasis and poor prognosis in CRC patients." (PMID 33344634, 2020).
malaria (2 papers, 2012 to 2018). Malaria is a serious and sometimes fatal disease caused by a parasite that commonly infects a certain type of mosquito which feeds on humans. "Strikingly, Rab14 silencing caused a two-fold increase in the percentage of malaria parasites phagocytosed by macrophages, as measured by flow cytometry." (PMID 22911692, 2012). "We confirmed that CD36 is a receptor involved in the phagocytosis of the malaria parasite P. berghei and found that when Rab14 is silenced the levels of surface CD36 increase, which can explain the increase in phagocytosis we have observed previously." (PMID 30158654, 2018). "Macrophages react specifically when infected with malaria parasites, upregulating the expression of several Rabs, including Rab14." (PMID 30158654, 2018). "Here, we investigated the mechanism by which the malaria parasite Plasmodium berghei and the bacterium Escherichia coli subvert phagocytosis through the modulation of Rab14 or Rab9a expression, respectively." (PMID 30158654, 2018). "In conclusion, our results show that the increase in phagocytosis of malaria parasites or E. coli, observed after Rab14 or Rab9a silencing, respectively, is due to an increase in the surface expression of the phagocytic receptors involved in the process." (PMID 30158654, 2018). "We have previously shown that Rab14 or Rab9a silencing leads to an increase in the phagocytosis of malaria parasites or E. coli, respectively." (PMID 30158654, 2018). "To confirm that CD36 plays a role in the increase in phagocytosis observed upon Rab14 silencing, we cultured macrophages treated with siRNA for Rab14 with erythrocytes infected with malaria parasites in the presence of CD36 blocking antibody." (PMID 30158654, 2018). "To study if the malaria parasite modulates the expression of Rab GTPases to its own benefit, we attempted to silence one of the Rab GTPases affected, namely Rab14, and look for any changes in the phagocytosis of the parasite." (PMID 22911692, 2012). "Further studies should address the mechanism by which Rab14 plays a role in microbial infection, and in particular how an increase in Rab14 expression inhibits phagocytic uptake of erythrocytes infected with the malaria parasite." (PMID 22911692, 2012). "Therefore, it seems that both malaria parasites and mycobacteria manipulate Rab14 to their own advantage, with the ultimate objective of avoiding degradation." (PMID 22911692, 2012). "Since we observed that silencing of Rab14 induced an increase in the phagocytosis of the malaria parasite, we hypothesized that overexpression of Rab14 would have the opposite effect." (PMID 22911692, 2012). "Moreover, we counted the number of infected cells by microscopy and confirmed the increase in phagocytosis of the malaria parasite after Rab14 silencing." (PMID 22911692, 2012). "The analysis of the cell population that did not overexpress Rab14 showed that around 25% of these cells had internalized malaria parasites." (PMID 22911692, 2012). "The results showed that, compared to the negative control, the live malaria parasite was able to induce an increase in the expression of Rab1a, Rab1b, Rab7a, Rab10, Rab14, Rab20, Rab27a, Rab32 and Rab38." (PMID 22911692, 2012).
melanoma (2 papers, 2022 to 2023). A malignant, usually aggressive tumor composed of atypical, neoplastic melanocytes. "We first generated Sec24c, Gcc2, Rab14 and Npc1 pooled CRISPR-KO B16 melanoma cells and implanted them in C57BL/6 wild-type mice." (PMID 36379959, 2022).
viral diseases (2 papers, 2022 to 2024). "As a host factor required for viral infection, Rab14 has also been shown to be involved in the replication of viruses such as human immunodeficiency virus (HIV), Ebola virus (EBOV), and classical swine fever virus (CSFV)." (PMID 39024394, 2024).
allergic asthma (1 paper, 2011). A asthma with a basis in a pathological type I hypersensitivity reaction. "It is localized on chromosome 9q33.2, in LD with two other genes that regulate inflammation and significantly associated with allergic asthma, GSN and RAB14." (PMID 21359210, 2011).
co-infection (1 paper, 2025). "To test this hypothesis, we transfected HeLa cells with GFP-tagged Rab14 and Rab35 and used our Inc co-infection model to evaluate Inc and Rab binding to CpoS." (PMID 41251378, 2025).
colon cancer (1 paper, 2024). "For example, a study revealed that DUXAP8 targeted miR-577 and promoted the expression of oncogene RAB14, which promoted colon cancer cell proliferation and progression." (PMID 38808892, 2024).
depression (1 paper, 2020). "Also, RAB14 expression in human brain tissue has been linked to depression and suicide, as was Syntaphilin, a protein that regulates synaptic vesicle processing and encoded by SYNPH, a gene associated to one of the top 10 CpG sites from the meta-analysis." (PMID 31992121, 2020).
developmental delay (1 paper, 2024). "In contrast, RAB14 and MYCN, other risk genes for developmental delay, exhibited peaks in later stages, which coincided with neuroblast differentiation into excitatory neurons during the fetal second trimester." (PMID 39363111, 2024).
Diabetes (1 paper, 2020). "In addition, the significant correlation was detected between Rab13 and Rab14 (r = 0.8971, p = 0.000) in the groups with diabetes (diabetic control group and diabetic OLP-treated groups), while between Rab8A and Rab13, and Rab8A and Rab14, results were not significant." (PMID 33256066, 2020). "To test this hypothesis, we investigated the effect of olive leaf polyphenols (OLP) on Rab8A, Rab13, and Rab14, as well as GLUT4 in the soleus muscle of rats with streptozotocin-induced diabetes (SZT)." (PMID 33256066, 2020).
Encephalopathy (1 paper, 2023). Encephalopathy is a term that means brain disease, damage, or malfunction. "For example, the mRNA expression trend of NF1, RAB14, ADCY5, and RAPGEF3 in the blood is the same as that in encephalopathy, suggesting that the purpose of assessing brain state can be achieved by detecting blood-related indicators." (PMID 36923118, 2023).
gastric adenocarcinoma (1 paper, 2017). "Quantitative real-time PCR (qRT-PCR) was performed in 17 gastric adenocarcinoma tissues and 4 cell lines to detect the expression of Rab14." (PMID 28107526, 2017).
kidney cancer (1 paper, 2021). Primary or metastatic malignant neoplasm involving the kidney. "In kidney cancer cells, Rab14 expression is significantly up-regulated, which promotes the proliferation, invasion, and metastasis of tumor cells and enhances the chemotherapy resistance of tumor cells." (PMID 34282711, 2021). "In kidney cancer cells, RAB14, which is a target gene of miR-148a, promotes the growth and metastasis of tumor cells, and enhances the chemotherapy resistance of tumor cells." (PMID 34282711, 2021).
pancreatic cancer (1 paper, 2022). "Overexpression of RAB14 has been demonstrated in pancreatic cancer and was corelated with poor prognosis." (PMID 36471277, 2022).
tumor (30 papers, 2012 to 2025). "In HCC, our prior collaborative work demonstrated that CHML escorts Rab14 to the membrane, sustaining Rab14 recycling to enhance tumor cell migration and invasion." (PMID 40842592, 2025). "In various tumor cells, RAB14 affects the development of tumor by regulating the proliferation, migration and invasion of tumor cells." (PMID 34282711, 2021). "In osteosarcoma, the circRNA hsa_circ_0005909/miR-338-3p/HMGA1 axis promotes tumor cells proliferation; the CASC15/miR-338-3p/RAB14 axis induces tumor cells growth, migration, and invasion in vitro and in vivo." (PMID 34718336, 2021). "As a tumor promoter, RAB14 regulates the invasion and metastasis of BC cells by activating the MAPK signaling pathway." (PMID 34869304, 2021). "Previous studies demonstrate that miR-577 is a well-recognized tumor suppressor and it negatively regulates a lot of oncogenes and oncogenic pathways, including Sphk2, Smurf1, Rab14, Rab25, LRP6, β-catenin, Wnt2b, and so on." (PMID 33069244, 2020). "Since Mucin13 and CD44 were well-known central players in tumor metastasis, we chose the two molecules to clarify the role of Rab14-positive vesicle in metastasis regulated by CHML." (PMID 31175290, 2019). "Previously, we have shown that miR-451 functions as a tumor suppressor in NSCLC by targeting ras-related protein 14 (RAB14)." (PMID 25026294, 2014). "Rab14 is an experimentally validated direct target of miR-451 and has been shown to activate tumour suppression." (PMID 23170974, 2012). "Moreover, compared with the adjacent non-tumor tissues, RAB14 expression was dramatically increased in OSCC tissues and the overexpression of miR-19b-3p promoted the mRNA and protein expression of RAB14." (PMID 34282711, 2021). "Here, we investigated the expression of Rab14 in GC tumor tissues and cell lines." (PMID 28107526, 2017). "Zhang et.al have identified Rab14 protein as a possible tumor marker for lung cancer." (PMID 28107526, 2017). "Phosphorylation of RCP at Ser435 by Lemur tyrosine kinase-3 (LMTK3) and of EphA2 at Ser897 by Akt are both necessary to promote Rab14-dependent (and Rab11-independent) trafficking of EphA2 which generates cell:cell repulsion events that drive tumour cells apart." (PMID 28294115, 2017). "Compared to the matched non-tumor gastric tissues and normal gastric epithelial cell lines, the expression of Rab14 was up-regulated in both tumor tissues and cell lines which suggested that Rab14 might be a tumor oncogene in human GC." (PMID 28107526, 2017). "As the expression levels of RAB14 protein were inversely correlated with the expression levels of miR-451 in NSCLC tissues it was concluded that downregulation of RAB14 may be the mechanism by which miR-451 carries out its tumor suppressor functions." (PMID 24999473, 2014). "Additionally, the tumor suppressor nischarin has been found to regulate early metastatic events in BC, with further research demonstrating its novel role in preventing BC cell motility and tumor growth by regulating Rab14 activity and secreting exosomes that control tumor malignancy." (PMID 38780753, 2024). "Recent studies suggest that RAB14 might act as an important regulator in tumor advancement." (PMID 33344634, 2020). "Additionally, expression levels of the downstream markers ZEB-2 and RAB-14 were downregulated, while those of the tumor suppressors CDKN2A, P63, and SIRT-1 were upregulated in the non-tumor specimens of LC patients with underlying respiratory disease compared to non-COPD patients." (PMID 29371906, 2018). "Gcc2-deleted or Rab14-deleted cancer cells induce T-cell and IFN-dependent anti-tumour immunity and inhibit tumour growth in mice." (PMID 36379959, 2022). "These miRNAs are known tumor suppressors that alter activity of many genes involved in tumorigenesis including TGFβR1, MUC4, ARHGAP, and RAB14." (PMID 29137392, 2017).
tumor (continued). "This mutation has not been described before, but recent findings reported RAB14 as an oncogene that is involved in the trafficking of tumor derived EVs by enhancing the angiogenic potential of endothelial cells." (PMID 40157906, 2025). "Furthermore, High RAB14, LC3 and Beclin1 expression was positively correlated with malignant features such as lymph node metastasis (P < 0.01), tumor staging (P < 0.05), tumor differentiation (P < 0.05)." (PMID 37558664, 2023). "To investigate whether SNHG15 and miR‐338‐3p exert tumor growth promoting function by modulating FOS/RAB14, we checked the effect of FOS and RAB14 on SNHG15‐induced cell proliferation." (PMID 30945457, 2019). "Moreover, we further revealed that SNHG15 executed tumor‐promoting function by sponging miR‐338‐3p and increasing the expression and activities of FOS and RAB14 for the first time." (PMID 30945457, 2019). "Given that Rab14 interacts with RCP, and N-cadherin has been found to promote the motility and invasion of tumour cell lines, we investigated whether RCP knockdown could also affect N-cadherin protein levels." (PMID 29285208, 2017). "Additionally this tumour contained a deletion surrounding CDKN2A/B, and an amplification of the RAS-related oncogene RAB14 on chr9q33.2." (PMID 27843499, 2016). "Also, miR-451 was found to be significantly correlated with tumor differentiation, pathological stage, lymph node metastasis and poor prognosis of patient, and further researches indicated that miR-451 could inhibit growth and enhance apoptosis of NSCLC cells by targeting RAB14." (PMID 25026294, 2014).
cancer (16 papers, 2011 to 2025). A tumor composed of atypical neoplastic, often pleomorphic cells that invade other tissues. "Combined targeting of RAB14 and Akt pathway is a possible strategy for dysregulation of cancer metastasis, one of the major causes of poor prognostic outcomes among BLCA patients." (PMID 37558664, 2023). "Transfection of pre-miR-214-3p was associated with a significant decrease in RAB14 mRNA levels in all 3 cancer cell lines." (PMID 36471277, 2022). "Increased miR-214-3p expression was associated with a marked decrease in RAB14 protein expression in all 3 cancer cell lines." (PMID 36471277, 2022). "This was associated with markedly enhanced RAB14 protein expression in the cancer cell lines compared to hESO cells assessed by Western blot." (PMID 36471277, 2022). "To date, there has only been few reports on the association between Rab14 and human cancers." (PMID 28107526, 2017). "Because basal levels of miR-214-3p are low in the cancer cell lines, transfection of pre-miR-214-3p into these cells was performed in order to assess the effects on RAB14 protein expression." (PMID 36471277, 2022). "In LUAD cells, ectopic expression of miR-451a inhibits cancer cell proliferation and enhances apoptosis via targeting of RAB14 and AKT signaling pathways." (PMID 30813343, 2019). "It has been suggested that RAB7 regulate autophagy pathway to facilitate cancer cell invasions as well as metastasis, we supposed that RAB14 could promote cell migration and invasion by regulating autophagy." (PMID 37558664, 2023). "RAB14 has been proved as an oncogene in various cancer types." (PMID 37558664, 2023). "To our knowledge, for the first time, we demonstrated that RAB14 regulated cancer cell autophagy." (PMID 37558664, 2023). "In order to show that these effects on migration and invasion seen after miR-214-3p manipulation were mediated by changes in RAB14 expression, these experiments were repeated following RAB14 silencing in the cancer cell lines and RAB14 overexpression in hESO cells." (PMID 36471277, 2022). "Moreover, RAB14, one of the targeted genes of miR-338-3p, acts as a cancer promoter in NSCLC." (PMID 34718336, 2021). "Therefore CHML might promote cancer metastasis through metastasis regulators in Rab14-positive vesicles, and further studies were required to clarify the involvement of specific cargo proteins in the metastasis-promoting role of CHML–Rab14 axis." (PMID 31175290, 2019). "This miRNA promotes cell proliferation and invasion by targeting RAB14.These findings suggest that the TRIM6-related miRNAs identified in this study may not only play functional roles in AML but also warrant further investigation in the context of other cancer types." (PMID 40961099, 2025). "Rab14 is a member of RAS oncogene family, and its dysfunction has been reported to be involved in various types of human cancer." (PMID 28107526, 2017). "miR-451 plays critical role in cancer cellular growth, migration, invasion in various of cancers by targeting MMIF, PI3k/Akt, RAB14, LKB1/AMPK." (PMID 24788655, 2014). "To identify whether cancer migration and invasion are involved in EMT, we explore the effect of RAB14 on EMT markers, including epithelial marker (E-cadherin) and mesenchymal marker (vimentin)." (PMID 37558664, 2023). "The significantly upregulated proteins RAB14 (Ras-related protein Rab-14) and HCFC1 (Host cell factor 1) in IDC and ILC with the ER- and PR-positive, HER2-negative patients (cancer No. 415 and NATs No. 112) were analyzed from mRNA level based on the TCGA database." (PMID 37064116, 2023).